RNF150 (ring finger protein 150)
Synonyms: KIAA1214
Tractability: Antibody: UniProt predicts a signal peptide or a membrane-spanning region. PROTAC: ubiquitination databases record sites on it.
Gene: Protein-coding gene on chromosome 4 (140,859,807 to 141,212,877, reverse strand). Ensembl gene ENSG00000170153.
Subcellular location: Membrane
Gene Ontology:
Molecular function: ubiquitin protein ligase activity
Biological process: ubiquitin-dependent protein catabolic process
Cellular component: membrane
Genetic constraint (gnomAD): Loss-of-function variants: 21 observed, 30.77 expected, observed/expected ratio (o/e) 0.68, 90% interval 0.48 to 0.98. The upper end of that interval is the gene's LOEUF score, 0.98, which puts it in group 4 of 6, group 1 being the genes least tolerant of losing a copy. Missense variants: 461 observed, 534.63 expected, observed/expected ratio (o/e) 0.86, 90% interval 0.8 to 0.93. Synonymous variants: 241 observed, 211.58 expected, observed/expected ratio (o/e) 1.14, 90% interval 1.02 to 1.27.
Homologues: Orthologues: chimpanzee RNF150 (99% identical), macaque RNF150 (98% identical), rabbit RNF150 (97% identical), pig RNF150 (97% identical), mouse Rnf150 (95% identical), rat Rnf150 (94% identical), dog RNF150 (82% identical), tropical clawed frog rnf150 (82% identical), zebrafish rnf150a (68% identical), guinea pig RNF150 (62% identical), Drosophila melanogaster gol (34% identical), Caenorhabditis elegans H10E21.5 (28% identical). Paralogues in human: RNF130 (46% identical), RNF149 (37% identical), RNF128 (36% identical), RNF133 (26% identical), RNF148 (25% identical), RNF13 (20% identical), RNF167 (18% identical), RNF215 (15% identical), ZNRF4 (15% identical).
Diseases named in the same sentence as RNF150 in open-access papers:
RNF150 is named in the same sentence as 4 diseases in open-access papers, as found by Europe PMC text mining. Sharing a sentence is not in itself a finding about the gene and the disease. The quoted sentences say what the papers report.
gastric cancer (2 papers, 2023 to 2024). A primary or metastatic malignant neoplasm involving the stomach. "Lastly, colorectal and gastric cancers exhibit a shared emphasis on the genes DES, RNF150, and CHRDL1, highlighting a common gene influence pattern." (PMID 39596491, 2024).
neoplastic diseases (2 papers, 2020 to 2023). "In addition, all urinary proteins, except for four (TMEM132A, HLA-DRB1, SLC10A3, RNF150), have been reported as candidate biomarkers for thirty-five neoplastic diseases." (PMID 36918772, 2023).
carcinoma (1 paper, 2024). A malignant tumor arising from epithelial cells. "A contrasting pattern of similarity emerges among carcinomas originating from uterine, pulmonary, and hepatic tissues, where genes like CTHRC1, ADH1B, GHR, DES, SFRP1, and RNF150 share similar weights." (PMID 39596491, 2024).
RNF150 also shares sentences with these, for which no sentence is quoted: breast carcinoma (2 papers).